ABCC5 (ATP binding cassette subfamily C member 5)
Description:
ATP-dependent transporter of the ATP-binding cassette (ABC) family that actively extrudes physiological compounds, and xenobiotics from cells. Mediates ATP-dependent transport of endogenous metabolites such as cAMP and cGMP, folic acid and N-lactoyl-amino acids (in vitro). Also acts as a general glutamate conjugate and analog transporter that can limit the brain levels of endogenous metabolites, drugs, and toxins. Confers resistance to the antiviral agent PMEA. Able to transport several anticancer drugs including methotrexate, and nucleotide analogs in vitro, however it does with low affinity, thus the exact role of ABCC5 in mediating resistance still needs to be elucidated. Acts as a heme transporter required for the translocation of cytosolic heme to the secretory pathway. May play a role in energy metabolism by regulating the glucagon-like peptide 1 (GLP-1) secretion from enteroendocrine cells (By similarity).
Synonyms: MOAT-C; MRP5; SMRP; EST277145; ABC33; MOATC; pABC11
Tractability: Small molecule: a structure with a bound ligand is known; a high-quality ligand is known; it belongs to a druggable protein family. Antibody: UniProt places it where antibodies can reach, with high confidence; its Gene Ontology location is reachable by antibodies, with high confidence; UniProt predicts a signal peptide or a membrane-spanning region; the Human Protein Atlas places it where antibodies can reach. PROTAC: ubiquitination databases record sites on it; a small molecule that binds it is known.
Target class: ABCC subfamily; ATP-binding cassette; Transporter; Primary active transporter
Safety:
Unwanted effects reported when the protein is acted on. In parentheses: how it was acted on, where the effect was seen, and who reports it.
grade 3–4 severe diarrhea (source: ClinPGx)
Neutropenia (source: ClinPGx)
Gene: Protein-coding gene on chromosome 3 (183,919,934 to 184,017,939, reverse strand). Ensembl gene ENSG00000114770.
Subcellular location: Basolateral cell membrane; Golgi apparatus lumen; Endosome membrane; Cytoplasmic granule; Apical cell membrane
Subcellular location (Human Protein Atlas): Cell Junctions; Plasma membrane; Nucleoplasm
Pathways (Reactome):
Drug ADME: Azathioprine ADME; Paracetamol ADME
Metabolism: Hyaluronan metabolism
Transport of small molecules: ABC-family protein mediated transport
Gene Ontology:
Molecular function: ABC-type 3',5'-cyclic GMP transmembrane transporter activity; ABC-type transporter activity; ABC-type xenobiotic transporter activity; efflux transmembrane transporter activity; glutathione transmembrane transporter activity; heme transmembrane transporter activity; purine nucleotide transmembrane transporter activity; xenobiotic transmembrane transporter activity; ATP binding; ATPase-coupled transmembrane transporter activity; transmembrane transporter activity; ATP hydrolysis activity
Biological process: cAMP transport; cGMP transport; export across plasma membrane; folate transmembrane transport; glutathione transmembrane transport; heme transmembrane transport; hyaluronan biosynthetic process; purine nucleotide transport; xenobiotic transport; carbohydrate derivative transport; transmembrane transport; transport across blood-brain barrier; xenobiotic detoxification by transmembrane export across the plasma membrane; xenobiotic metabolic process; xenobiotic transmembrane transport; guanine nucleotide transmembrane transport
Cellular component: apical plasma membrane; basolateral plasma membrane; endosome membrane; Golgi lumen; membrane; plasma membrane
Genetic constraint (gnomAD): Loss-of-function variants: 58 observed, 158.59 expected, observed/expected ratio (o/e) 0.37, 90% interval 0.29 to 0.46. The upper end of that interval is the gene's LOEUF score, 0.46, which puts it in group 2 of 6, group 1 being the genes least tolerant of losing a copy. Missense variants: 1,240 observed, 1,802.1 expected, observed/expected ratio (o/e) 0.69, 90% interval 0.66 to 0.72. Synonymous variants: 632 observed, 701.37 expected, observed/expected ratio (o/e) 0.9, 90% interval 0.84 to 0.96.
Homologues: Orthologues: chimpanzee ABCC5 (99% identical), macaque ABCC5 (99% identical), guinea pig ABCC5 (97% identical), dog ABCC5 (96% identical), rabbit ABCC5 (95% identical), mouse Abcc5 (95% identical), rat Abcc5 (95% identical), pig ABCC5 (83% identical), tropical clawed frog abcc5 (82% identical), zebrafish abcc5 (73% identical), Drosophila melanogaster MRP (32% identical), Drosophila melanogaster Mrp5 (30% identical), and 9 more. Paralogues in human: ABCC12 (42% identical), ABCC11 (38% identical), ABCC1 (34% identical), ABCC2 (33% identical), ABCC4 (32% identical), ABCC3 (31% identical), ABCC10 (30% identical), ABCC6 (30% identical), ABCC9 (29% identical), ABCC8 (29% identical), CFTR (24% identical).
Diseases named in the same sentence as ABCC5 in open-access papers:
ABCC5 is named in the same sentence as 76 diseases in open-access papers, as found by Europe PMC text mining. Sharing a sentence is not in itself a finding about the gene and the disease. The quoted sentences say what the papers report.
breast cancer (22 papers, 2012 to 2025). A primary or metastatic malignant neoplasm involving the breast. "ABCC5 is associated with resistance to many drugs and it has been studied for example to promote metastasis to bone in breast cancer." (PMID 36809527, 2023). "ABCC5 is described as differentially spliced in SF3B1 mutated breast cancer, and MRPS21 is described as a gene, whose upregulation is associated with poor response to azacytidine in MDS and related cancers." (PMID 34499147, 2021). "Together, these data demonstrate that loss of ABCC5 function in breast cancer cells results in decreased osteoclast numbers within bone-metastatic lesions." (PMID 23174366, 2012). "Our results indicated that ABCC5 expression was associated with pemetrexed resistance in vitro and in vivo, and it may serve as a target or biomarker for the optimization of pemetrexed regimen in breast cancer treatment." (PMID 33632224, 2021). "For example, CD44 and ABCC5 are highly expressed in breast cancer with bone metastasis and can serve as potential markers for this metastatic site." (PMID 40500539, 2025). "The findings indicate that ABCC5 was most highly expressed in breast cancer cells exhibiting a bone metastasis phenotype in the absence of therapy (anti-oestrogen, chemotherapy, or bisphosphonates)." (PMID 39563862, 2024). "It has been reported that ABCC5 contributes to bone metastasis in breast cancer by increasing the generation of osteoclasts and encouraging osteolytic bone breakdown." (PMID 39563862, 2024). "ABCC5 transports cyclic nucleotides, including the metabolites of 5‐fluorouracil (5‐FU), a common anticancer agent used in both breast cancer and colon cancer treatment." (PMID 35906899, 2023). "The rest of the genes above were also over-expressed metastatic cancers originating from breast cancer (ABCC5), kidney renal clear carcinoma (LRFN1), hepatocellular carcinoma (ELOVL6), and uveal melanoma (HTR2B)." (PMID 34680307, 2021). "Currently, knockdown of miR-128 in breast tumor-initiating cells was reported to induce chemotherapeutic resistance, which contributes to chemotherapeutic resistance in breast cancers by targeting of Bmi-1 and ATP binding cassette subfamily C member 5 (ABCC5)." (PMID 33472642, 2021). "The enhanced ABCC5 level was shown to be related to the occurrence of breast cancer, hepatocellular carcinoma, and pancreatic ductal adenocarcinoma." (PMID 32952599, 2020). "We identified ABCC5 as a gene that is overexpressed in breast cancer bone metastases compared with primary breast tumors." (PMID 23174366, 2012). "Our data support a role for ABCC5 in promoting the specific growth of breast cancer cells within the bone microenvironment through a mechanism that favors osteoclast formation and/or function." (PMID 23174366, 2012). "One interesting result was the observation that the density of TRAP-positive osteoclasts was reduced in lesions formed by breast cancer cells harboring reduced ABCC5 levels compared with bone metastases arising from control cells." (PMID 23174366, 2012). "ABCC5, an ATP-dependent transporter, was found to be overexpressed in breast cancer osseous metastases relative to primary breast tumors." (PMID 23174366, 2012). "Given the availability of antibody reagents, we focused our attention on ABCC5, a candidate gene that was found to be significantly overexpressed in breast cancer skeletal metastases relative to primary tumors by both microarray-based and RT-qPCR methods." (PMID 23174366, 2012). "Together, these results support an important functional role for ABCC5 in promoting the colonization and growth of breast cancer cells specifically within the bone." (PMID 23174366, 2012). "ABCC5 expression in breast cancer cells is important for efficient osteoclast-mediated bone resorption." (PMID 23174366, 2012).
breast cancer (continued). "As a first step to validate functionally a role for ABCC5 in promoting bone metastasis, we interrogated the expression of ABCC5 in breast cancer cell lines with high bone-metastatic potential." (PMID 23174366, 2012). "The osteoclast precursors were subsequently stimulated with conditioned media from the 4T1-derived populations, which exhibited the most-pronounced difference in osteoclast numbers between control and ABCC5 knockdown breast cancer cells in vivo." (PMID 23174366, 2012). "We next determined the level of ABCC5 expression in mouse-derived breast cancer cells with differential metastatic abilities." (PMID 23174366, 2012). "To confirm this functional role for ABCC5 in promoting breast cancer metastasis to bone, we analyzed the effects of reduced ABCC5 expression on the ability of 4T1 breast cancer cells to form bone metastases after cardiac injection." (PMID 23174366, 2012). "Although a significant body of literature has linked ABCG2 expression with drug resistance in breast cancer, considerably less is known about ABCA5 and ABCC5 in this disease." (PMID 23174366, 2012). "ABCC5 was found to be functionally involved in the formation of breast cancer bone metastases in two independent cell-based models." (PMID 23174366, 2012). "To address this possibility, we examined ABCC5 expression in breast cancer cell populations that exhibit a bone-metastatic phenotype." (PMID 23174366, 2012). "We focused on ABCC5 (MRP5) as a candidate mediator of breast cancer skeletal metastases because we validated its expression in bone metastases at both the mRNA and protein levels." (PMID 23174366, 2012). "Moreover, the survival rate of breast cancer patients with high ABCC5 expression over 50 years old was lower than that of patients under 50 years old." (PMID 39563862, 2024). "Breast cancer cells that develop bone metastases overexpress ABCC5." (PMID 39563862, 2024). "MRP5 (ABCC5) also confers resistance against pemetrexed in breast cancer." (PMID 37239055, 2023). "In addition, biological effects of ABCC5 in breast cancer, colon cancer, pancreatic cancer, and nasopharyngeal carcinoma have also been reported." (PMID 36193204, 2022). "Subsequently, we assessed the potential role of ABC transporters in conferring resistance to pemetrexed in primary breast cancer cells isolated from 34 breast cancer patients and the role of ABCC5 in mediating pemetrexed transport and apoptotic pathways in MCF-7 cells." (PMID 33632224, 2021). "Finally, the influence of ABCC5 expression on the therapeutic effect of pemetrexed was evaluated in an in vivo xenograft mouse model of breast cancer." (PMID 33632224, 2021). "ABCC5 functions have been regarded as a mediator of breast cancer skeletal metastasis." (PMID 30367091, 2018). "To determine whether ABCC5 is important for the ability of breast cancer cells to metastasize to bone, we stably diminished ABCC5 expression in bone-metastatic breast cancer cell lines by using short-hairpin RNAs (shRNAs)." (PMID 23174366, 2012). "Importantly, diminished ABCC5 expression in human and mouse mammary cancer cell lines did not affect their proliferative properties in vitro or their in vivo growth as mammary tumors." (PMID 23174366, 2012). "To better define the mechanisms responsible for impaired bone metastasis in mice injected with the ABCC5-knockdown breast cancer cell populations, we examined the density of osteoclasts present within lytic lesions formed by the MDA-MB-231 and 4T1-derived cells." (PMID 23174366, 2012). "Finally, ABCC5 was functionally validated in in vivo models to be an important mediator in breast cancer outgrowth in this organ." (PMID 23174366, 2012). "Thus, it is conceivable that elevated ABCC5 expression is selected for because of a particular function that enables breast cancer cells to colonize the bone microenvironment efficiently." (PMID 23174366, 2012).
breast cancer (continued). "This hypothesis might explain the specific requirement for ABCC5 expression in breast cancer cells that metastasize to the bone." (PMID 23174366, 2012). "To investigate potential explanations for the reduction in the size of osteolytic lesions arising in mice injected with breast cancer cells engineered to express ABCC5 shRNAs, we examined the proliferative and apoptotic indices in both mammary tumors and bone metastases." (PMID 23174366, 2012). "Our data suggest that ABCC5 functions as a mediator of breast cancer skeletal metastasis." (PMID 23174366, 2012). "Whether breast cancer cells that express ABCC5, and thus maintain low cytoplasmic cGMP levels through active efflux, are associated with elevated MMP-9 expression or secretion requires further investigation." (PMID 23174366, 2012). "Furthermore, immunohistochemical analysis revealed that ABCC5 protein levels appeared to be enriched in breast cancer bone metastases compared with primary mammary tumors." (PMID 23174366, 2012). "Alternatively, an as-yet-unidentified ABCC5 cargo may be responsible for enhanced osteoclast differentiation and motility that leads to the formation of osteolytic breast cancer metastases in bone." (PMID 23174366, 2012). "In addition, ABCC5 was significantly upregulated in human and mouse breast cancer cell lines with high bone-metastatic potential." (PMID 23174366, 2012). "ABCC5 may be a potential therapeutic target for breast cancer bone metastasis." (PMID 30367091, 2018). "Hence, ABCC5 is a novel candidate mediator of breast cancer bone metastasis, which may be a potential target for the development of treatment for this detrimental disease." (PMID 23174366, 2012). "ABCC5 expression was inversely correlated with pemetrexed sensitivity (IC50, r = 0.741; p < 0.001) in breast cancer cells derived from 34 patients." (PMID 33632224, 2021). "Tumor suppressor miR-128 sensitized breast cancers to DOX by targeting ABCC5, while the overexpression of miR-145 suppressed ABCC1/MRP1 to overcome DOX resistance in breast cancers." (PMID 32883003, 2020). "To determine whether loss of ABCC5 was associated with elevated levels of apoptosis, we performed immunohistochemical staining for cleaved caspase-3 in both mammary tumors and bone metastases that arose in mice injected with 1833-BM1- or 4T1-derived breast cancer populations." (PMID 23174366, 2012). "Hence, ABCC5 may be a potential therapeutic target for breast cancer bone metastasis." (PMID 23174366, 2012). "Intriguingly, several members of the ATP-binding cassette (ABC) transporter superfamily (ABCA5, ABCC5, and ABCG2) were consistently overexpressed in breast cancer bone metastases compared with primary breast tumors." (PMID 23174366, 2012). "Diminished ABCC5 expression resulted in a significant reduction in the size of osteolytic lesions formed by both 1833-BM1 and 4T1 breast cancer cell models when compared with controls." (PMID 23174366, 2012). "Intriguingly, three members of the ATP-binding cassette (ABC) transporter family (ABCA5, ABCC5, ABCG2) were overexpressed in breast cancer bone metastases compared with primary tumors that are metastatic to bone." (PMID 23174366, 2012). "MRP5 (ABCC5) expression also plays an essential role in osteoclast-mediated bone resorption, and it may be a predictable marker for bone metastasis in breast cancer." (PMID 37239055, 2023). "Similar to our results with the human breast cancer cell-line model, suppression of ABCC5 expression in mouse breast cancer cell lines did not result in the alteration of the total number of bone metastases per mouse." (PMID 23174366, 2012). "Diminished ABCC5 expression did not result in elevated apoptosis in either end-stage mammary tumors or end-stage osteolytic bone metastases." (PMID 23174366, 2012). "Consistently, no change in breast cancer cell proliferation, in either primary breast tumors or bone metastases, was noted when ABCC5 was knocked down compared with controls." (PMID 23174366, 2012).
breast cancer (continued). "Finally, we did not observe any differences in breast cancer cell apoptosis in response to a stimulator of cGMP production (A-350619 hydrochloride) in control or ABCC5 knockdown cells (data not shown)." (PMID 23174366, 2012). "Finally, conditioned media from breast cancer cells with reduced ABCC5 expression failed to induce in vitro osteoclastogenesis to the same extent as conditioned media from breast cancer cells expressing ABCC5." (PMID 23174366, 2012). "Moreover, the removal of ABCC5 did not result in elevated rates of apoptosis in either primary tumors or breast cancer bone metastases, as assessed with immunostaining for cleaved caspase-3." (PMID 23174366, 2012). "A study used breast cancer cell lines with different metastatic potentials, including human MDA-MB-231 (bone and lung metastatic sublines) and mouse 4T1 (non-metastatic and lung metastatic sublines), to show that ABCC5 expression is highest in bone metastatic cells." (PMID 39563862, 2024).
pancreatic cancer (14 papers, 2010 to 2025). "Expression of these genes, which are involved in 5-FU conversion to FdUMP, also correlated with expression of the FdUMP efflux transporter ABCC5 (TK1 and ABCC5 r = 0.78, p = 0.001 and TYMP and ABCC5 r = 0.86, p < 0.0001) in pancreatic tumour." (PMID 34132895, 2021). "The ABCC11 gene, which was highly expressed in liver samples in addition to ABCC5, was expressed at a very low level in pancreatic tumour." (PMID 34132895, 2021). "Three out of them (ABCC2, ABCC5, ABCC8) have been already described for their association with drug resistance in pancreatic cancer." (PMID 29285254, 2017). "Furthermore, miR-210 overexpression inhibits pancreatic cancer growth and reverses gemcitabine resistance by directly targeting the multi-drug efflux transporter ABCC5, a crucial factor in drug resistance in various cancers." (PMID 38139352, 2023). "Thus, it is not likely that FdUMP efflux through ABCC11 contributes to 5-FU drug resistance as much as ABCC5 in pancreatic cancer." (PMID 34132895, 2021). "Since the substrate sets of ABCA1-2, ABCB1, ABCC5, and ABCG2 overlap, the general effect of SOX9 suppression on overall or partial drug resistance of pancreatic cancer cells in context of these ABC proteins cannot be predicted with certainty." (PMID 40141294, 2025). "In pancreatic cancer, ABCG2, ABCC1, ABCC5, and ABCA8 have been specifically reported to be associated with gemcitabine resistance, whereas additional ABC transporters are widely expressed in chemoresistant PDAC cells." (PMID 39000545, 2024). "Previous work investigated that chemoresistance in pancreatic cancer cells was via regulating the expressions of MDR genes including ABCB1, ABCC1, ABCC3 and ABCC5." (PMID 26709920, 2015).